BMP2 (bone morphogenetic protein 2)
Diseases named in the same sentence as BMP2 in open-access papers (continued):
Sharing a sentence is not in itself a finding about the gene and the disease.
colorectal cancer (28 papers, 2011 to 2025). A primary or metastatic malignant neoplasm that affects the colon or rectum. "A recent study suggests that TRAIL produced from SMAD4-deficient colorectal cancer cells induces BMP2 in fibroblasts, which enhances invasiveness and metastasis of colorectal cancer." (PMID 33810241, 2021). "BMP-2 specifically has been implicated in suppressing tumor development in human colorectal cancer cells." (PMID 32933207, 2020). "In these, 8 SNPs were annotated to the same gene in pairs of height- and colorectal cancer risk-associated SNPs, leading to the following four gene annotations: BMP2, PITX1, DCBLD1, and BARX1." (PMID 28117334, 2017). "BMP2 is a member of the TGF-β superfamily which has been associated with colorectal cancer." (PMID 27107574, 2016). "Among these, BET1L and OAS1 were previously unreported in colorectal cancer studies, while BMP2 had been identified in European populations, highlighting both novel and shared genetic risk factors across ancestries." (PMID 40303978, 2025). "In contrast, the downregulation of BMP2 in colorectal cancer further impedes DNA replication and chemotherapy resistance." (PMID 38627856, 2024). "As a member of the transforming growth factor-β super-family, enhanced expression of bone morphogenetic protein 2 (BMP2) can check the growth of colorectal cancer cells, enhance apoptosis, and reduce tumor development in the body." (PMID 35601497, 2022). "BMP2 is down‐regulated in colorectal cancer tissues while also being able to suppress colorectal cancer progression." (PMID 33611848, 2021). "However, BMP2 has also been reported to suppress colorectal cancer cell growth by inhibiting proliferation and inducing apoptosis." (PMID 29416020, 2018). "Interestingly, a recent study demonstrated that BMP2 inhibited the proliferation of human colorectal cancer cells using adenovirus infection and the piggyBac transposon-mediated stable BMP2 overexpression." (PMID 26029998, 2015). "Here we demonstrate that transforming E. coli with a cDNA encoding an ileal-derived mature human BMP-2 induces effective apoptosis in an in vitro model system for colorectal cancer, whereas the maternal organism was not effective in this respect." (PMID 22315590, 2012). "Furthermore, BMP2 has been identified as a differentiating and radiosentizing agent for colorectal cancer stem cells, suggesting that restoring the BMP signaling pathway may offer novel therapeutic approaches for colorectal cancer." (PMID 38049682, 2023). "Additionally, as key players of UPR, activating transcription factor 6 (ATF6) upregulation and ATF4 downregulation activates PI3K/AKT/mTOR signaling but reduces Bone Morphogenetic Protein 2 (BMP2) signaling in colorectal cancer cells to enhance motility and invasion via EMT." (PMID 36890838, 2023). "Expression of BMP2, BMP4, BMP5, BMP6, BMP9 and osteocalcin has been reported in colorectal cancer with heterotopic ossification." (PMID 29029440, 2017). "The high level of BMP2 gene methylation in colorectal cancer is a negative prognostic marker typical for the third stage of the disease." (PMID 35216235, 2022). "BMP2 is a member of transforming growth factor superfamily with a regulatory role in adult tissue homeostasis, reported to be significantly down-regulated in recurrent metastases compared to non-metastatic colorectal cancer." (PMID 28768481, 2017).
atherosclerosis (26 papers, 2014 to 2025). A disease characterized by the build-up of fatty material and calcium deposition in the arterial wall resulting in partial or complete occlusion of the arterial lumen. "HG increases the expression of BMP-2 and enhances the calcification of VSMCs, while elevated plasma BMP-2 levels are associated with atherosclerosis burden and coronary mineralization in type 2 diabetes." (PMID 34502172, 2021). "BMP4 is increased in response to a high fat diet (a risk factor for atherosclerosis), which then up-regulates BMP2 levels." (PMID 28646109, 2017). "Transgenic over-expression of BMP-2 under the direction of the SMA promoter accelerated intimal calcification in ApoE-deficient mice with atherosclerosis." (PMID 25603410, 2015). "Specifically, BMP2 is inflammatory mediators in endothelial cells, and its elevated activity can promote atherosclerosis and vascular calcification." (PMID 41561153, 2025). "The role of BMP2 in vascular calcification, atherosclerosis and inflammation is well established, but only one study evaluated the BMP-2 levels in HD patients." (PMID 38535084, 2024). "Bone morphogenetic protein 2 (BMP-2) is a cytokine that is elevated in the process of atherosclerosis and contributes to the vascular inflammation and calcification associated with uremia." (PMID 37629118, 2023). "Bone morphogenetic protein (BMP)‐2 is a cytokine which has been recently shown to be elevated in atherosclerosis and T2DM and to contribute to vascular inflammation." (PMID 30102472, 2018). "Our results suggest that BMP‐2, by increasing adhesion of monocytes on ECs, contributes to the increased inflammatory responses during atherosclerosis." (PMID 30102472, 2018). "Previous studies have demonstrated that BMP-2 plays a crucial role in osteoblast differentiation in the development of atherosclerosis and calcific vascular lesions." (PMID 29895327, 2018). "IL-37 was reported to ameliorate symptoms of atherosclerosis and arterial calcification via its influence on BMP-2 mediated ALP expression." (PMID 29641433, 2018). "Other studies suggest that BMP2 and BMP4 are linked to the development of atherosclerosis, and BMP antagonist neuroblastoma suppressor of tumorigenicity 1 (NBL1, accession number X66872.1) specifically antagonizes BMP2, BMP4 and BMP14." (PMID 29596467, 2018). "Our findings also show that BMP9 and BMP10 synergize with TNFα to induce expression of BMP2, which is a known regulator of endothelial inflammation and plays a role in atherosclerosis." (PMID 28646109, 2017). "Amongst these differentially expressed genes, we noted a positive association between BMPR1A-biased BMP2 expression and GPR176, an orphan G-protein coupled receptor thought to be involved in atherosclerosis." (PMID 27114889, 2016). "A growing body of evidence indicates that BMP-2 signaling plays an important role in vascular disease, including atherosclerosis, plaque instability, and vascular calcification and inflammation." (PMID 26003174, 2015). "The purpose of this study is to evaluate the relationship of BMP-2 with atherosclerosis and calcification in patients with T2DM." (PMID 26003174, 2015). "BMP-2 plays a proinflammatory role in early atherosclerosis." (PMID 36909186, 2023). "Furthermore, it is also known that NF-ĸB selectively modulates BMP-2 mRNA expression and that BMP-2 exerts its pro-inflammatory effects by inducing monocyte migration and adhesiveness to endothelial cells, contributing to the development of atherosclerosis." (PMID 37629118, 2023). "In addition, BMP-2 plays a critical role in vascular disease, including atherosclerosis and plaque instability through its effects on vascular inflammation." (PMID 33661896, 2021).
atherosclerosis (continued). "Interestingly, BMP2 also regulates a set of genes enriched in FoxO signaling, insulin resistance, and fluid shear stress and atherosclerosis, suggesting potential links to trophoblast metabolic regulation and trophoblast-endothelial cell remodelling." (PMID 34970543, 2021). "The premise and results of our investigation may seem to disagree with a number of studies reporting that BMP‐2 contributes to vascular calcification, and thus atherosclerosis." (PMID 31737960, 2020). "Moreover, Bmp2 facilitates osteoblast differentiation, bone mineralization, atherosclerosis, and vascular calcification." (PMID 30971745, 2019). "We demonstrate that BMP‐2 may exert its pro‐inflammatory function in atherosclerosis by endorsing monocyte recruitment, their adhesion to the endothelium and by interfering with monocyte‐to‐macrophage differentiation into the anti‐inflammatory M2 macrophages." (PMID 30102472, 2018). "Whether the effects of BMP‐2 on atherosclerosis development are also due to its effects on monocyte function is not known." (PMID 30102472, 2018). "Our findings provide novel insights into the mechanisms by which BMP‐2 may contribute to the development of atherosclerosis." (PMID 30102472, 2018). "Monocyte adhesion on extracellular matrix and on ECs plays a crucial role in the development of atherosclerosis, thus we investigated whether BMP‐2 affects monocyte adhesion." (PMID 30102472, 2018). "Altogether our results provide novel insights into the mechanisms by which BMP‐2 exerts its pro‐inflammatory effects and in this way may contribute to the development of atherosclerosis." (PMID 30102472, 2018). "In addition, while BMP-2 is a known mediator of vascular calcification, the role of BMP-2 in the development of atherosclerosis remains uncertain, particularly amongst T2DM patients." (PMID 26003174, 2015). "We provide additional insight into the pathophysiology of atherosclerosis, and inhibition of BMP-2-induced myosin Va expression may represent a potential therapeutic strategy." (PMID 24790701, 2014). "Inhibition of BMP-2-induced myosin Va expression may represent a potential future therapeutic strategy attenuating atherosclerosis." (PMID 24790701, 2014). "In addition, it has been postulated that BMP-2 may be used to treat disorders such as multiple sclerosis, cardiovascular disease, anemia, atherosclerosis, renal calcification, and kidney failure." (PMID 32933207, 2020). "Hence, BMP‐2 may contribute to the development of atherosclerosis by inducing the infiltration of mononuclear cells in the vessel wall." (PMID 30102472, 2018). "BMP2 plays an important role in vascular biology, and increased BMP-2 levels can promote inflammation and atherosclerosis through oxidative stress and endothelial dysfunction." (PMID 37008310, 2023). "It was reported that BMP-2 produced by VSMCs from atherosclerotic lesions promotes monocyte recruitment and inflammation by activating BMPR II in an early atherosclerosis mouse model." (PMID 36909186, 2023). "BMP2, ERK/MAPK, and PI3K/AKT signaling pathways induce RUNX2 expression in VSMC, promoting vascular calcification and atherosclerosis while pharmacological inhibition or degradation of RNUX2 can reduce calcification." (PMID 36923537, 2023). "Thus, BMP‐2 may be a therapeutic target for prevention of atherosclerosis." (PMID 30102472, 2018). "As NBL1 is a specific antagonist of BMP2 and BMP4, both of which promote atherosclerosis, NBL1 is capable to inhibit atherosclerosis." (PMID 29596467, 2018). "In addition, genes related to the TGFβ pathway, such as BMP2 and TRPV4, the Wnt pathway, and the cell senescence signaling pathway can be targeted in arteries to prevent vascular calcification or atherosclerosis under diabetic or uremic conditions." (PMID 41465376, 2025).
atherosclerosis (continued). "It well-known that the expression of BMPR-2, the receptor for classic osteogenic ligands BMP-2 and BMP-4, is decreased in patients with advanced coronary atherosclerosis and it is protective against atherosclerosis in animal models, suggesting a context-specific role of BMPR-2-mediated signalling." (PMID 39768183, 2024). "Interestingly, the ability to induce M2 macrophage polarization seems to be shared with other BMP ligands since BMP2 promotes the acquisition of a M2 phenotype during bone regeneration and BMP-7 treatment increases M2 differentiation and reduces inflammation and plaque formation in atherosclerosis." (PMID 31337120, 2019).
gastric cancer (24 papers, 2010 to 2024). A primary or metastatic malignant neoplasm involving the stomach. "For example, BMP-2 has been associated with tumour progression in the late stages of gastric cancer." (PMID 38226014, 2024). "BMP2 causes the invasion and proliferation of gastric cancer cells through the activated PI3/Akt signalling pathway." (PMID 38627856, 2024). "BMP2 is associated with the occurrence of various cancers and can inhibit the proliferation of gastric cancer cells by downregulating EZH2." (PMID 37570275, 2023). "High levels of the osteoinductive cytokine BMP2 in the serum of patients with gastric cancer were shown to be associated with bone metastasis." (PMID 34064589, 2021). "Further, BMP-4 mRNA is preferentially overexpressed in poorly differentiated gastric cancer, and overexpression of BMP-2/4, -5 or BMPR-IA are all associated with malignancy of oral epithelium and may be involved in the metastasis of oral carcinoma cells." (PMID 22168923, 2011). "Mechanistical studies revealed that stimulation of gastric cancer cells with BMP2 leads to an activation of the AKT/NFKB/MMP9 axis and, thus, promotes EMT, motility, and invasion of these cells." (PMID 34064589, 2021). "In gastric cancer cells, BMP-2 enhanced the phosphorylation/degradation of IκBα and the nuclear translocation/activation of NF-κB, as well as phosphorylation of AKT and ERK, leading to MMP-9 expression." (PMID 28350359, 2017). "Increased serum levels of BMP-2 correlate with the grade of tumor histology and the depth of invasion in gastric cancer." (PMID 28350359, 2017). "BMP2/BMPR axis triggered Epithelial mesenchymal transition (EMT) process in gastric cancer, and then was involved in tumor cell migration, invasion and metastasis via the activation of PI3K/AKT and MEK/ERK pathways." (PMID 27886213, 2016). "RhBMP-2 increased both the mRNA and protein levels of BMP-2 in gastric cancer cells, which is in line with the microarray analysis of the activation of the BMP-2 signaling pathway." (PMID 27636990, 2016). "It has been reported that BMP-2 expression is frequently regulated by DNA hypermethylation in colorectal and gastric cancers." (PMID 25797254, 2015). "The stimulation of BMP2 in gastric cancer cells induces a full EMT characterized by Snail induction, E-cadherin delocalization and down-regulation, and up-regulation of mesenchymal and invasiveness markers." (PMID 25938545, 2015). "ASPN, an extracellular matrix protein, which inhibits TGF-β and BMP2, is overexpressed in the gastric cancers relative to the paired normal." (PMID 21092330, 2010). "Blocking the AKT signaling reduces the BMP2-mediated invasiveness of gastric cancer cells." (PMID 34064589, 2021). "BMP-2 promotes motility and invasion of gastric cancer cells by activating PI-3 kinase/Akt10." (PMID 27886213, 2016). "Moreover, high concentrations of BMP-2 strongly enhanced gastric cancer cell motility and invasiveness." (PMID 24946687, 2014). "Similarly, BMP2 has been shown to increase the expression of MMP9 in gastric cancer cells through AKT, ERK and NF-κB signaling cascades." (PMID 24053318, 2013). "Additionally, BMP-2 increases gastric cancer cell motility and invasion by activating PI-3 kinase/Akt; blocking this pathway may limit BMP-2-mediated metastasis." (PMID 36080338, 2022). "For instance, transforming growth factor-beta 1 (TGF-β1) and bone morphogenetic protein 2 (BMP2) were detected in plasma exosomes from gastric cancer patients and gastric cancer cell-derived exosomes, respectively." (PMID 36967787, 2023). "Since GREM1 functions as an antagonist against both BMP2 and BMP4, its upregulation would result in a general inhibition effect to the BMP signaling pathways in gastric cancer." (PMID 29720137, 2018).
gastric cancer (continued). "To address whether the treatment with rhBMP-2 in gastric cancer cells could increase the level of endogenous BMP-2 expression, we performed real-time RT-PCR to measure the endogenous BMP-2 expression following treatment with rhBMP-2 in SNU484 and SNU638 cells." (PMID 27636990, 2016). "But, most cancer patients had similar expression level of BMP2 and BMP4 as non-cancer patients, indicating that the expression of BMP ligands was not altered in gastric cancer." (PMID 29720137, 2018).